RNU2-72P (RNA, U2 small nuclear 72, pseudogene)
Gene: Small nuclear RNA gene on chromosome 10 (60,912,765 to 60,912,927, reverse strand). Ensembl gene ENSG00000223107.
Homologues: Orthologues: chimpanzee U2 (100% identical), macaque U2 (63% identical), mouse Gm25007 (48% identical), rabbit U2 (39% identical). Paralogues in human: RNU2-41P (52% identical), RNU2-23P (50% identical), RNU2-58P (48% identical), RNU2-10P (45% identical), RNU2-22P (45% identical), RNU2-16P (44% identical), RNU2-60P (44% identical), RNU2-28P (43% identical), RNU2-24P (41% identical), RNU2-55P (39% identical), U2 (38% identical), RNU2-12P (37% identical), and 66 more.